GLI1 (GLI family zinc finger 1)
Diseases named in the same sentence as GLI1 in open-access papers (continued):
Sharing a sentence is not in itself a finding about the gene and the disease.
gastric cancer (continued). "In gastric cancer, genistein decreases Gli1 gene expression and attenuates cancer stem-like properties." (PMID 34466474, 2019). "In gastric cancer, miR-133b expression was negatively associated with lymph node metastasis, and miR-133b targeting Gli-1 markedly inhibited gastric cancer metastasis." (PMID 31771219, 2019). "Once GLI1 was knocked down, the stem cell-like phenotype of gastric cancer MCAs decreased accordingly." (PMID 31366904, 2019). "Our study provides a basis for blocking GLI1 activity in the prevention and treatment of peritoneal metastases of gastric cancer." (PMID 31366904, 2019). "We implanted the same number of SGC7901 gastric cancer cells, which treated differently with control-shRNA or Gli1-shRNA onto the subcutaneous sites of mice and measured tumor size twice a week." (PMID 29321573, 2018). "We found there is a significant association between Gli1 and HER2 expression in gastric cancer specimens." (PMID 29321573, 2018). "After adding trastuzumab to gastric cancer cells, the expression level of Gli1 decreased while SMO remained unchanged." (PMID 29321573, 2018). "Whereas, in survival analysis of the 67 patients after surgery according to gastric cancer tissues IHC outcome, the differential expression of Gli1 related to different survival time (P < 0.05) while the HER2 didn’t (P = 0.170)." (PMID 29321573, 2018). "The expression level of Gli1 is an independent prognostic factor of the survival duration of gastric cancer patients after operation." (PMID 29321573, 2018). "This means HER2 regulates its main downstream pathway PI3K-Akt-mTOR34,35.Then we added rapamycin to gastric cancer cells, the expression level of p-p70S6k and Gli1 decreased while SMO remained unchanged." (PMID 29321573, 2018). "In our study, we detected 67 gastric cancer tissues and showed Gli1 was related to several clinicopathological factors, such as depth of tumor invasion, lymph node metastasis and TNM staging." (PMID 29321573, 2018). "To directly test the role of GLI1 for putative cancer stem cell maintenance, we detected the putative cancer stem cell population in gastric cancer cells using three methods." (PMID 28404967, 2017). "The expression of Gli1, a marker of Hh signaling activation, was higher in gastric cancer tissue than that in the adjacent normal tissue in our study." (PMID 28399898, 2017). "Consistent with mRNA expression, we also observed that the protein level of Gli1 was decreased and Smo was unchanged in itraconazole-treated gastric cancer cells." (PMID 28399898, 2017). "Since inhibitors for GLI1 are already available, we predict that these novel reagents, together with chemotherapy, will improve the overall survival of gastric cancer patients." (PMID 28413604, 2017). "Our results suggest that Hh signal pathway is activated in human gastric cancer and itraconazole can inhibit gastric cancer cells growth by inhibiting the expression of Gli1." (PMID 28399898, 2017). "Our results indicate that the GLI1-mediated regulation of ABCG2 is an important mechanism responsible for maintenance of the residual cancer cells (or putative cancer stem cells) in gastric cancer following treatment with CDDP, a major chemotherapeutical drug." (PMID 28404967, 2017). "We showed that GLI1 knockdown sensitized gastric cancer cells to CDDP whereas ectopic GLI1 expression decreased the sensitivity." (PMID 28404967, 2017). "SHH was mainly expressed in the cytoplasm and GLI1 protein was predominantly localized to the nucleus and cytoplasm in gastric cancer cells." (PMID 28399898, 2017). "Hh signaling is activated in gastric tumor and itraconazole can inhibit the growth of gastric cancer cells by inhibiting Gli1 expression." (PMID 28399898, 2017). "While in both subgroups divided by sample size, Gli-1 expression was correlated to high depth of invasion in gastric cancer patients (n ≤ 70: OR 6.92, 95%CI 1.72-27.88, P = 0.007; n > 70: OR 9.24, 95%CI 2.85-29.92, P = 0.000)." (PMID 27634907, 2016).
gastric cancer (continued). "Ten of eligible studies used the immunological histological chemistry (IHC) method to evaluate the expression of Gli-1 in gastric cancer tissues, the rest 2 studies used in situ hybridization (ISH) method." (PMID 27634907, 2016). "The relationship between Gli-1 expression in gastric cancer patients and clinicopathological features and 5-year overall survival (OS) was evaluated using pooled odds ratios (ORs) and hazard ratio (HR) with 95% confidence intervals (CIs)." (PMID 27634907, 2016). "On the whole, our results provide convincing proof of the correlation between aggressive biological behavior and Gli-1 overexpression in gastric cancer patients for the first time." (PMID 27634907, 2016). "We also detected the expression of Mel-18, CD44, CD133, Oct4, Sox2, and Gli1 expressions in gastric cancer cells using Western blot assay or QRT-PCR." (PMID 27542229, 2016). "Similar to the results of prognostic analysis for overall survival, CD44, Shh, and Gli1 status also affected the recurrence of gastric cancer in our study." (PMID 26839535, 2016). "Taken together, Gli-1 is a credible indicator for highly aggressive tumor with poor prognosis in gastric cancer patients." (PMID 27634907, 2016). "On the basis of these results, we propose a model by which Gal-1 promotes invasion and the EMT in gastric cancer via regulating Gli-1." (PMID 27835885, 2016). "We found that low-expression of Mel-18 was correlated with poor prognosis and negatively correlated with overexpression of stem cell markers Oct4, Sox2, and Gli1 in 101 gastric cancer tissues." (PMID 27542229, 2016). "It is necessary to further elucidate the mechanisms of aberrant Shh, Gli1 expression and the overexpression of CSCs markers in gastric cancer." (PMID 26839535, 2016). "Our work points to a novel function for Gal-1 in gastric cancer invasion by promoting the EMT via upregulation of Gli-1." (PMID 27835885, 2016). "Secondly, Gli-1 can be identified as a biomarker for poor prognosis in gastric cancer patients, which provides more guidance for clinical diagnosis and prognosis of these patients." (PMID 27634907, 2016). "Transcriptional factor Gli1 is a target of miR-202-3p and plays an essential role as a mediator of the biological effects of miR-202-5p in gastric cancer." (PMID 26556872, 2015). "Activity of luciferase with Gli1 3′-untranslated region was markedly decreased by miR-133b in gastric cancer cells." (PMID 24443799, 2014). "Increasing number of studies show that Gli1 is overexpressed in various cancers including gastric cancer, and the expression levels of Gli1 are positively correlated with tumor differentiation." (PMID 23936094, 2013). "We demonstrate that the transcriptional factor Gli1 was a target of miR-202-3p and plays an essential role as a mediator of the biological effects of miR-202-3p in gastric cancer." (PMID 23936094, 2013). "GLI1 is a downstream target of hedgehog (hh) signaling pathway which is essential to gastric cancer development and progression." (PMID 22799764, 2012). "Gli1 expression indicates a constitutive activation of the Hh pathway in gastric cancer cells, because Gli1 is a target gene of the Hh pathway." (PMID 20087349, 2010). "Our investigations revealed that these inhibitors could effectively modulate GLI1 expression and consequently intervene in the progression of gastric cancer, opening up new avenues for future therapeutic strategies." (PMID 40255562, 2025). "Therefore, blocking or silencing the expression of GLI1 will significantly help suppress gastric cancer progression." (PMID 40255562, 2025). "In addition, GLI1 protein level in gastric cancer tissues was significantly higher than that in tumor-adjacent tissues, which is consistent with the results of previous studies." (PMID 40255562, 2025).
gastric cancer (continued). "Our hypothesis is supported by reports from studies which have shown that FASN knockdown via siRNA can reduce Gli1 levels in gastric cancer cells, suggesting that FASN may contribute to tumorigenesis and metastasis." (PMID 40149597, 2025). "To verify whether there was an association between GLI1 and PRKACB, we analyzed the data using the TIMER database and found that the correlation coefficient between PRKACB and GLI1 expression in gastric cancer was the highest amongst the analyzed tumors." (PMID 40255562, 2025). "Similarly, overexpression of zinc finger protein GLI1 induces drug resistance in gastric cancer cells by binding to the AKT-mTOR pathway." (PMID 38370477, 2024). "GLI1 facilitates the EMT induced by TGF-β1 in gastric cancer." (PMID 38498906, 2024). "Nicotinamide adenine dinucleotide phosphate (NADPH) oxidase 4 (NOX4), a subunit of the NOX complex, has been demonstrated to drive reactive oxygen species generation, in turn contributing to cell proliferation and apoptosis of gastric cancer cells via activation of the GLI1 pathway." (PMID 38021154, 2023). "Importantly, studies have shown that NOX4 plays an important role in the growth and apoptosis of gastric cancer cells by producing ROS and activating GLI1 signaling." (PMID 35528617, 2022). "Hedgehog/Gli1 signaling pathway has been found to be frequently activated in gastric cancer." (PMID 35785165, 2022). "Additionally, it was demonstrated that MAPK pathway increased the transcriptional factors and regulated Gli1 through Hh/Suppressor of Fused (SUFU)-independent pathway in gastric cancer cell lines." (PMID 35834029, 2022). "Mechanistically, Gal-1 secreted by gastric cancer tissue-derived CAFs binds to β1 integrin, an important regulator of cancer cell invasion, to induce GLI1 expression and gastric cancer cell invasion, while siRNA-mediated knockdown of β1 integrin abrogated this effect." (PMID 34572373, 2021). "As Gal-1 was shown to modulate GLI1 expression to promote EMT, Gal-1 may have GLI1 as a mediator of the EMT pathway to induce VM in gastric cancer." (PMID 34572373, 2021). "Likewise, SPOP repression enhanced GLI1/2 levels, which consequently promoted gastric cancer cell proliferation and migration as well as attenuated apoptosis." (PMID 34572373, 2021). "In addition, miR-202-3p inhibits gastric cancer proliferation through inducing cell apoptosis by direct interaction with Gli1." (PMID 32764512, 2020). "Ras signaling induces Gli1 gene expression in gastric cancer." (PMID 33228057, 2020). "Noticeably, GLI1 was reported to be a direct target of miR-873-5p in gastric cancer." (PMID 32793474, 2020). "Next, we determined the expression of GLI1 in three kinds of gastric cancer cells and GES-1 cells." (PMID 30918291, 2019). "Yan and coworkers found that Gli1 overexpression is a frequent event in gastric cancer tissues,and is correlated with characteristics of a more aggressive phenotype, including poorly differentiated histology, advanced TNM stage, serosal involvement and lymph node metastasis." (PMID 30918291, 2019). "We retrospectively evaluated the impact of Gli1 on the outcomes of gastric cancer patients." (PMID 29321573, 2018). "To elaborate whether the expression levels of Gli1/HER2 in gastric cancer tissues exert an influence on overall survival of patients after gastrectomy, we analyzed survival curves according to target genes expression." (PMID 29321573, 2018). "These evidence may highlight a new therapeutic strategies to gastric cancer by Gli1 inhibitor applied." (PMID 29321573, 2018). "In conclusion, Gli1 is an important prognosis factor of gastric cancer." (PMID 29321573, 2018). "In conclusion, Gli1 is a favorable prognostic indicator in gastric cancer." (PMID 29321573, 2018).
gastric cancer (continued). "However, only venous invasion, HER2 expression, Gli1 expression were verified to be independent prognostic factors for the survival in gastric cancer patients after multivariate analysis (P < 0.05), especially Gli1 expression (P < 0.001)." (PMID 29321573, 2018). "It suggests that the synthetic therapy of Gli1 suppressor and trastuzumab may act as an effective therapy of gastric cancer." (PMID 29321573, 2018). "Furthermore, univariate and multivariate analysis revealed that venous invasion, HER2 expression, Gli1 expression were independent prognostic factors for the survival time in gastric cancer." (PMID 29321573, 2018). "The results demonstrated that itraconazole could inhibit proliferation of gastric cancer cells by inhibiting Gli1 expression." (PMID 28399898, 2017). "Thus, GLI1, the focus for the rest of our study, appears to be critical for drug resistance in gastric cancer cells." (PMID 28404967, 2017). "In our study, we showed that itraconazole could inhibit gastric cancer cells growth by regulating the expression of Gli1, which is in accordance with a previous study." (PMID 28399898, 2017). "Hh signaling is activated in gastric cancer tissues; inhibition of Gli1 expression might be at least partially responsible for the proliferation inhibitory effect of itraconazole in gastric cancer cells, which needs to be verified in the future." (PMID 28399898, 2017). "Hence, we investigated the effect of itraconazole on the expression of Hh-related molecules, including Shh, Ptched1, Ptched2, Smo and Gli1, in gastric cancer cells." (PMID 28399898, 2017). "In addition, miR-202 was shown to be a tumor suppressor that inhibited cell proliferation by targeting Gli1, a transcription factor of the Hh signaling pathway, in gastric cancer." (PMID 27322257, 2016). "Therefore, a quantitative meta-analysis was conducted to determine the clinical value of Gli-1 in gastric cancer patients." (PMID 27634907, 2016). "Similarly, it is also the first time to evaluate the overexpression of Shh and Gli1 proteins can predict worse survival outcome and early recurrence in gastric cancer." (PMID 26839535, 2016). "To identify whether SMO or Gli-1 are directly regulated by Gal-1, we treated Gal-1-overexpressing gastric cancer cell lines with cyclopamine (a SMO antagonist) or a siRNA specific to SMO and Gli-1 in the presence of rGal-1." (PMID 27835885, 2016). "However, the clinical evidence of the relationship between Gli-1 and tumor invasion or prognosis in gastric cancer is insufficient at present." (PMID 27634907, 2016). "In addition, in gastric cancer cells, the ectopic expression of Gli1 decreases nuclear β-catenin staining." (PMID 25713298, 2015). "It seems that miR-202-5p may function as a novel tumor suppressor in gastric cancer, and its anti-tumor activity may attribute the direct targeting and inhibition of Gli1." (PMID 26556872, 2015). "Furthermore, Gli1 expression was frequently positive in gastric cancer tissues and inversely correlated with miR-133b expression." (PMID 23936094, 2013). "Taken together, these findings suggest that miR-202-3p may function as a novel tumor suppressor in gastric cancer and its anti-tumor activity may attribute the direct targeting and inhibition of Gli1." (PMID 23936094, 2013). "Especially, previous studies found that FA2H (Fatty acid 2-hydroxylase) depletion could lead to decreased chemosensitivity to cisplatin via inhibition of AMPK and activation of mTOR/S6K1/Gli1 pathway in gastric cancer, and turn different cancer cells resistant to PM02734." (PMID 36003143, 2022). "The siRNA-mediated knockdown of GLI1 could also abolish Gal-1-induced gastric cancer invasion and expression of mesenchymal markers, including N-cadherin, vimentin, and SNAI1, and invasion-related protein MMP9, as well as restore the expression of the epithelial marker, E-cadherin." (PMID 34572373, 2021). "It suggests that Gli1 may act as a novel gastric cancer suppressor." (PMID 29321573, 2018).
gastric cancer (continued). "Furthermore, we determined whether elevated Hh signaling is sufficient to drive drug resistance in gastric cancer cells by ectopic expression of GLI1 in N87 and AGS cells, and examining their IC50 values for CDDP." (PMID 28404967, 2017). "Hence, a meta-analysis of published data was performed to systematically elucidate whether Gli-1 overexpression would have correlation with the tumorigenesis and prognosis in patients with gastric cancer." (PMID 27634907, 2016). "Furthermore, our data revealed that Gal-1 modulated the non-canonical Hh pathway by increasing the transcription of glioma-associated oncogene-1 (Gli-1) via a Smoothened (SMO)-independent manner, and that upregulation of Gal-1 was strongly associated with gastric cancer metastasis." (PMID 27835885, 2016). "So, Ptch or Gli1 might be an alternative target for treatment of gastric cancer." (PMID 21394208, 2011). "Furthermore, enhanced bcl-2 expression may be as a result of Gli-1 re-expression as confirmed in gastric carcinoma cells." (PMID 17505514, 2007). "GLI1 and PRKACB expression was examined using immunohistochemistry in tissue microarrays containing 30 gastric cancer and 30 tumor-adjacent tissue samples." (PMID 40255562, 2025). "GLI1 protein levels were significantly higher in gastric cancer tissues than in tumor-adjacent tissue samples, consistent with PRKACB protein levels in gastric cancer tissues." (PMID 40255562, 2025). "Zinc mainly contributes to gastric cancer cell resistance through zinc finger proteins such as ZFP64, GLI1, ZFP91, ZNF139, which regulate gastric cancer cell resistance through pathways such as GAL-1, MALAT1, AKT-mTOR, or by modulating miRNA." (PMID 38370477, 2024). "In a prior study, the KRAS proto-oncogene of the MAPK/ERK pathway was found to boost the transcriptional activity of GLI1 and the expression of SHH pathway target genes in gastric cancer." (PMID 36900220, 2023). "In gastric cancer, doxorubicin-resistant cells that overexpress SHH and GLI1, the well-known signaling molecules involved in drug resistance, are susceptible to GLI inhibition with GANT61 and vismodegib via downregulation of its downstream effector ABCG2." (PMID 37176108, 2023). "From a database analysis, PRMT5, MEP50, and GLI1 target genes are all upregulated in known HH signaling pathway-activated cancers, including SCLC, gastric cancer, skin basal carcinoma, and breast cancer." (PMID 32859041, 2020). "CXC chemokine receptor 4 (CXCR4), which is a prognostic marker for gastric cancer, leukemia, and other cancers, and can increase levels of its downstream molecule LCP1, is activated by the regulator GLI1." (PMID 31360146, 2019). "In gastric cancer, KRAS positively modulates tumor proliferation increasing GLI1 transcriptional activity and expression of HH target genes." (PMID 31244888, 2019). "That is to say, inhibit Gli1 both via HER2–Akt–mTOR–p-70S6K and Hedgehog pathway has synergistic effect on gastric cancer cells." (PMID 29321573, 2018). "The result showed the expression levels of Gli1 and HER2 were significantly higher in gastric cancer than in para-cancer tissues (P < 0.001 and P < 0.001)." (PMID 29321573, 2018). "Here we found Gli1 and HER2 are highly expressed in gastric cancer tissues, and they are positively related." (PMID 29321573, 2018). "Our study showed the expression levels of Gli1 and HER2 were significantly higher in gastric cancer than in para-cancer tissues." (PMID 29321573, 2018). "We detected the expression level of Gli1 and HER2 in the 67 primary human gastric cancer tissues and paired adjacent healthy tissues by immunohistochemistry (IHC)." (PMID 29321573, 2018). "We predict that the novel strategies aimed at reducing GLI1 expression or interrupting ABCG2 function, together with CDDP-based chemotherapy, should improve the survival of gastric cancer patients." (PMID 28404967, 2017).